CYP51A1 (cytochrome P450 family 51 subfamily A member 1)
Diseases named in the same sentence as CYP51A1 in open-access papers:
CYP51A1 is named in the same sentence as 81 diseases in open-access papers, as found by Europe PMC text mining. Sharing a sentence is not in itself a finding about the gene and the disease. The quoted sentences say what the papers report.
fungal infections (22 papers, 2011 to 2025). "Specifically, azole CYP51A1 inhibitors have been developed and are widely used in medicine and agriculture to treat fungal infections." (PMID 38672427, 2024).
hepatocellular carcinoma (4 papers, 2020 to 2025). A malignant tumor that arises from hepatocytes. "In parallel, small-molecule inhibitors targeting human CYP51A1 have been developed and tested in hepatocellular carcinoma models, supporting its therapeutic relevance." (PMID 40659633, 2025). "For instance, 25-hydroxycholesterol suppresses CYP51A1 mRNA levels in both human adrenocortical H295R and hepatocellular carcinoma HepG2 cells under cholesterol-deprived conditions." (PMID 40659633, 2025). "Additionally, the transcription factor YY2 has been identified as an endogenous repressor of CYP51A1 and can suppress cholesterol biosynthesis and tumor progression in hepatocellular carcinoma." (PMID 40659633, 2025). "Additionally, nitric oxide (NO) induces rapid post-translational downregulation of CYP51A1 protein in human Huh7 hepatocellular carcinoma cells." (PMID 40659633, 2025). "Likewise, LK-935, a pyridylethanol(phenylethyl)amine derivative, binds to the heme pocket of CYP51A1, similar to azoles, and suppresses sterol synthesis in hepatoma cells." (PMID 40659633, 2025). "Intriguingly, cholesterol deprivation upregulates CYP51A1 in H295R but not in HepG2 cells, suggesting cell-type-specific regulatory mechanisms that could be leveraged to suppress hepatocellular carcinoma growth." (PMID 40659633, 2025).
lung carcinoma (4 papers, 2020 to 2022). "Remarkably, knockdown of CYP51A1 significantly inhibited the in vitro mobility and invasiveness of the lung cancer cell lines A549 and CL1-5." (PMID 35805888, 2022). "Moreover, overexpression of CYP51A1, HMGCS1, and FDFT1 caused an increase in migration/invasion capabilities of cells in vitro, suggesting a positive association between these proteins and invasiveness of lung cancer cells." (PMID 35805888, 2022).
colorectal cancer (3 papers, 2016 to 2023). A primary or metastatic malignant neoplasm that affects the colon or rectum. "CYP51A1 expression is increased in poor prognosis colorectal cancers in comparison with good prognostic tumors." (PMID 35805888, 2022). "This study found increased expression of CYP51A1 in primary colorectal cancer compared with normal colonic mucosa." (PMID 27341022, 2016). "This study has profiled the expression of the cholesterol metabolising enzymes CYP2R1, CYP7B1, CYP8B1, CYP27A1, CYP39A1, CYP46A1 and CYP51A1 in primary colorectal cancer tissue using a well-characterised cohorts of colorectal cancers." (PMID 27341022, 2016). "However, CYP2R1 (p=0.034), CYP8B1 (p=0.002), CYP39A1 (p<0.001), CYP46A1 (p<0.001) and CYP51A1 (p=0.001) each demonstrated significantly reduced expression in paired lymph node metastasis compared to Dukes C (stage 3) colorectal cancer." (PMID 27341022, 2016). "CYP2R1, CYP7B1, CYP8B1, CYP46A1 and CYP51A1 all showed significantly increased expression in primary colorectal cancer compared to normal colonic mucosa with CY7B1 demonstrating the highest proportion of strong immunoreactivity in colorectal cancer compared to all other enzymes studied." (PMID 27341022, 2016). "Immunohistochemistry was performed on a colorectal cancer tissue microarray containing 650 primary colorectal cancers using monoclonal antibodies to CYP2R1, CYP7B1, CYP8B1, CYP27A1, CYP39A1, CYP46A1 and CYP51A1, which we have developed." (PMID 27341022, 2016). "The intensity of immunostaining was significantly higher in primary colorectal cancer compared with normal colonic mucosa for CYP2R1 (p<0.001), CYP7B1 (p<0.001), CYP8B1 (p<0.001), CYP46A1 (p<0.001) and CYP51A1 (p=0.001)." (PMID 27341022, 2016).
Alzheimer disease (2 papers, 2022 to 2025). A progressive, neurodegenerative disease characterized by loss of function and death of nerve cells in several areas of the brain leading to loss of cognitive function such as memory and language. "A study investigating DNA methylation in CYP genes using circulating cfDNA from Alzheimer’s disease (AD) patients identified significant CpG site changes in CYP51A1 and CYP2S1." (PMID 40080233, 2025).
breast carcinoma (2 papers, 2020 to 2023). "The CYP51A1 rs37417517 variant was found to be associated with the female-specific breast cancer and variant rs229188 with female genetics." (PMID 33182326, 2020).
Hepatic failure (2 papers, 2017 to 2020). "Only two studies are reporting the CYP51A1 deleterious mutations, which resulted in infant liver failure and death." (PMID 33182326, 2020). "Therefore, we propose to include selected CYP51A1 variants into personalized diagnostics panel for evaluating risks for pediatric cataract, neonatal hepatic failure, global developmental delay, azole susceptibility, and cardiovascular and metabolic diseases." (PMID 28713270, 2017). "We propose to include damaging CYP51A1 variants in genetic testing to increase the discovery of underlying causes for diseases such as pediatric cataract neonatal hepatic failure, global developmental delay, azole susceptibility, and cardiovascular and metabolic diseases." (PMID 28713270, 2017).
metastatic prostate carcinoma (2 papers, 2012 to 2025). A carcinoma that arises from the prostate gland and has spread to other anatomic sites. "The eight genes where higher expression was associated with worse prognosis (CYC, CYP51A1, DHFR, EBP, KIF15, PPM1D, SQLE, and UMPS) represent potential additional therapeutic targets in metastatic prostate cancer." (PMID 40405591, 2025). "Eight genes (CYC, CYP51A1, DHFR, EBP, KIF15, PPM1D, SQLE, and UMPS) demonstrated strong dependency in cell lines and were also associated with worse prognosis clinically, representing potential therapeutic targets in metastatic prostate cancer." (PMID 40405591, 2025). "Ketoconazole and Itraconazole, as 14-α demethylase (CYP51A1) inhibitors, are synthetic antifungal drugs and could be used to treat refractory bone pain and neurologic injury in patients with advanced metastatic prostate cancer." (PMID 22589709, 2012).
ovarian carcinoma (2 papers, 2023). A malignant neoplasm originating from the surface ovarian epithelium. "A similar pattern of expression for CYP51A1 mRNA was also displayed in ovarian cancers, though low protein expression was detected in less than 10% of the ovarian cancer samples examined." (PMID 38001897, 2023). "In contrast, CYP51A1 protein was significantly expressed in almost half of patients with primary ovarian cancer compared to its weak expression in almost 10% of normal ovary samples." (PMID 38001897, 2023).
Antley-Bixler syndrome (1 paper, 2025). Antley-Bixler syndrome is a very rare disorder characterized by craniosynostosis with midface hypoplasia, radiohumeral synostosis, femoral bowing and joint contractures. "Moreover, dysregulation of CYP51A1 has been implicated in a wide spectrum of diseases, such as cancer, cataracts, Antley-Bixler syndrome, autoimmune disorders, metabolic liver disease and neurodegeneration." (PMID 40659633, 2025).
autoimmune conditions (1 paper, 2025). "Furthermore, aberrant expression or function of CYP51A1 has been linked to multiple human diseases, including cancer, congenital syndromes, autoimmune conditions, metabolic liver disease, and neurodegenerative disorders." (PMID 40659633, 2025).
autoimmune disorders (1 paper, 2025). "Recent evidence suggests that CYP51A1, a key enzyme in cholesterol biosynthesis, may influence immune cell function and thereby contribute to autoimmune disease development." (PMID 40659633, 2025).
BOR syndrome (1 paper, 2024). "In this study, we demonstrate pathogenicity of EYA1 c.1698+1G>A, propose a mechanism for dysfunction of mutant EYA1, and conjecture CYP51A1 as a potential genetic modifier of renal involvement in BOR syndrome." (PMID 38213489, 2024). "In addition, we here suggest CYP51A1 to potentially play a role as genetic modifier of renal involvement in BOR syndrome." (PMID 38213489, 2024).
cataract (1 paper, 2025). Partial or complete opacity of the crystalline lens of one or both eyes that decreases visual acuity and eventually results in blindness. "Given the genetic heterogeneity of pediatric cataracts, further integrative genomic studies are warranted to define the precise contribution of CYP51A1 to lens development and to explore its potential as a diagnostic marker or therapeutic target in congenital cataract syndromes." (PMID 40659633, 2025).
congenital cataracts (1 paper, 2025). "The presence of CYP51A1 mutations in patients with congenital cataracts—often accompanied by hepatic or neurological symptoms—suggests its dual role in ocular development and systemic homeostasis." (PMID 40659633, 2025). "Another study investigating 115 cataract-associated genes in 36 unrelated patients with syndromic or nonsyndromic bilateral congenital cataracts found one patient harboring compound heterozygous mutations in CYP51A1 (I312T and Y421X, rs141654764)." (PMID 40659633, 2025). "In a cohort study of 38 children with congenital cataracts, a missense mutation in CYP51A1 was identified in one family." (PMID 40659633, 2025). "In support of this, patients carrying the L232P mutation in CYP51A1 presented with congenital cataracts, neonatal cholestatic jaundice, elevated liver enzymes, and hyperferritinemia, indicating that CYP51A1 mutations may underlie a syndromic disorder affecting both ocular and hepatic systems." (PMID 40659633, 2025).
diabetes (1 paper, 2018). "In the current study, the expression of CYP51A1 was inhibited, which will cause the upregulation of the NF-κB signaling pathway, leading to the upregulation of TNF-α, which will then trigger an inflammatory reaction and aggravate the symptoms of diabetes." (PMID 30131712, 2018).
Follicular Cyst (1 paper, 2023). Cyst due to the occlusion of the duct of a follicle or small gland.
glioma (1 paper, 2017). A benign or malignant brain and spinal cord tumor that arises from glial cells (astrocytes, oligodendrocytes, ependymal cells). "In addition, densely plated glioma cells were more sensitive to CYP51A1 inhibition than sparse, consistent with our data showing that this pathway is dysregulated in dense cancer cells." (PMID 28118603, 2017). "Finally, we found that glioma cells, but not normal astrocytes, are sensitive to shutting down cholesterol synthesis through pharmacological inhibition of lanosterol synthase or CYP51A1 in a density-dependent manner." (PMID 28118603, 2017).
heart failure (1 paper, 2021). Inability of the heart to pump blood at an adequate rate to meet tissue metabolic requirements. "The CYP51A1 deficiency in mice shows heart failure and lethality owing to heart hypoplasia, vasculogenesis, ventricle septum, and epicardial defects." (PMID 34456633, 2021).
multiple sclerosis (1 paper, 2021). A progressive autoimmune disorder affecting the central nervous system resulting in demyelination. "The two-way analysis to identify genes differentially expressed in CSF versus bloodin multiple sclerosis versus non-inflammatory controls yielded four significantgenes: LRRD1, CYP51A1, PASK andYes1." (PMID 34761221, 2021).
myeloma (1 paper, 2022). "Moreover, since CYP51A1 is MM-specifically upregulated in chronic hypoxia, the development and investigation of selective CYP51A1 inhibitors may be a promising strategy for anti-myeloma treatment." (PMID 35053409, 2022).
renal carcinoma (1 paper, 2024). A carcinoma arising from the epithelium of the renal parenchyma or the renal pelvis. "Based on our experimental findings, we have conjectured that the downregulation of CYP51A1 in renal cancer tissues triggers an escalation in endogenous cholesterol biosynthesis through the NF-κB signaling pathway, thereby instigating tumor progression." (PMID 38993563, 2024).
cancer (17 papers, 2011 to 2025). A tumor composed of atypical neoplastic, often pleomorphic cells that invade other tissues. "Mutations or dysregulated expression of human CYP51A1 are implicated in diverse diseases, including cancer, genetic syndromes, neurological disorders, metabolic liver disease and immune dysfunction." (PMID 40659633, 2025). "While CYP51A1 overexpression is frequently associated with cancer progression, emerging strategies explore the potential therapeutic benefit of its hyperactivation under select conditions." (PMID 40659633, 2025). "The fairly low somatic mutation frequency of CYP51A1, its druggability, as well as the possibility of interfering with cholesterol metabolism in cancer cells collectively suggest the clinical importance of CYP51A1." (PMID 33924405, 2021). "Obtained results suggest further exploration of polyphenols for the cholesterol lowering ability and anti-cancer potential via CYP51A1." (PMID 33924405, 2021). "CYP51A1 gene knockout blocked de novo cholesterol synthesis, while CYP51A1 inhibition led to the induction of apoptosis in cancer cells, indicating the clinical significance of this protein." (PMID 33924405, 2021). "Overall, flavonoids have the potential to inhibit the activity of human CYP51A1 and should be further explored for their cholesterol-lowering and anti-cancer activity." (PMID 33924405, 2021). "Subsequent inhibition of WEE1 G2 checkpoint kinase (WEE1) kinase results in synthetic lethality, highlighting how manipulating upstream or downstream pathways of CYP51A1 may promote selective cancer cell death." (PMID 40659633, 2025). "Deciphering how CYP51A1-mediated sterol metabolism impacts the tumor and its microenvironment may reveal new therapeutic strategies for cancer prevention and treatment." (PMID 40659633, 2025). "Camptothecin amplified the effects seen in cancer (CHECK2, BCL-2 and IL8), but opposed them for CYP51A1, ITGA2, DHCR7 or HMGCS1." (PMID 28962550, 2017). "In a study screening commercial and experimental CYP51A1 inhibitors for anti-cancer activity, only VFV, a compound with a bulky imidazole-oxadiazole core, showed potent anti-proliferative effects across multiple cancer cell types." (PMID 40659633, 2025). "Some of these treatments could oppose the deregulations occurring in cancer samples, including those of the CHECK2, CYP51A1, HMGCS1, ITGA2, NME1 or VEGFA genes." (PMID 28962550, 2017). "For example, human cytochrome c1, whose gene is regulated by E2F, participates in an electron transport chain and the mitochondria pathway of apoptosis whereas a similar set of electron transport-related genes (COX8, CYB5-M, CYP51A1, FDXR and SUCLG1) were found to be E2F4-bound in cancer cell lines." (PMID 22076139, 2011).
tumor (10 papers, 2014 to 2025). "Expression of CYP51A1 was associated with tumour differentiation and mismatch repair protein status." (PMID 27341022, 2016). "Additionally, the COSMIC database revealed the presence of somatic CYP51A1 point mutations in tumor samples, some also with a predicted deleterious effect on activity." (PMID 33182326, 2020). "Of note, within tumor samples, the expression level of CYP51A1 in mRCC was relatively diminished compared to pRCC (GSE105261: P=0.0016; GSE73121: P=7.9e-10)." (PMID 38993563, 2024). "When compared with the control group, tumors in the si-CYP51A1 group grew significantly faster (P < 0.01) and their tumor wet weights increased significantly (P < 0.01)." (PMID 38993563, 2024). "We found the expression of CYP51A1 was downregulated in tumor tissues compared with normal tissues (P = 3.5e-07)." (PMID 38993563, 2024). "CYP7B1, CYP8B1, CYP39A1, CYP46A1 and CYP51A1 each displayed a statistically significant relationship with location of tumour in the colon versus the rectum." (PMID 27341022, 2016). "When the anatomical site of the tumour was stratified as proximal colon, distal colon or rectum, significant associations were found with expression of CYP8B1, CYP27A1 and CYP51A1." (PMID 27341022, 2016). "Thus, CYP51A1-regulated cholesterol intermediates can function as immunometabolic signals that shape both tumor cell behavior and the immune landscape." (PMID 40659633, 2025). "Dysregulation of CYP51A1 activity may contribute to tumor progression by altering apoptotic sensitivity and shaping an immunosuppressive tumor microenvironment." (PMID 40659633, 2025). "Additionally, this elucidates that CYP51A1 can suppress tumor proliferation by modulating the NF-KB pathway." (PMID 38993563, 2024). "The eventual involvement of lncRNA ENST00000453068 as a regulator of the neighboring gene CYP51A1 in tumor cells in response to drugs could be the subject of future studies." (PMID 24905231, 2014). "To elucidate the role of CYP51A1 in immune escape within the tumor microenvironment, we conducted multiplex immunohistochemistry on RCC, RCC-TT, and para-tumor tissues to assess CYP51A1 expression across various cell types in these tissues." (PMID 38993563, 2024). "These comprehensive results emphasize the multi-faceted influence of CYP51A1 on RCC, portraying its involvement in tumor growth, migration, and wound healing dynamics." (PMID 38993563, 2024). "Strong immunostaining for CYP51A1 was demonstrated in 21.9% of tumours and CYP8B1 immunoreactivity was classified as strong in 18.9% of tumours." (PMID 27341022, 2016). "In the Th17 lineage, RORC (receptor) is upregulated on the tumor infiltrating CD4+ T-cells and its ligands (CYP51A1, FDFT1, HSD17B7, LBR, TM7SF2, MSMO1, NSDHL) are also upregulated on the tumor cells, implying GBM expresses ligands that induces Th17 phenotype in tumor infiltrating helper T-cell." (PMID 34012510, 2021). "When the primary tumours of lymph node positive cases (Dukes C, stage 3) were compared to the paired lymph node metastasis, expression of CYP2R1, CYP8B1, CYP39A1, CYP46A1 and CYP51A1 were each significantly reduced in the lymph node metastasis." (PMID 27341022, 2016).
kidney disease (1 paper, 2024). "CYP51A1 variants are rare and have not previously been associated with kidney disease." (PMID 38213489, 2024). "However, while these findings are in line with the notion that heterozygous CYP51A1 depletion or dysfunction may not become apparent per se, they do not rule out a potential modifier role of the gene for kidney disease." (PMID 38213489, 2024).
neurodevelopmental disorder (1 paper, 2025). A behavioral and cognitive disorder with onset during the developmental period that involves impaired or aberrant development of intellectual, motor, or social functions. "In support of a broader role in neurodevelopmental disorders, whole-genome sequencing of 327 children with cerebral palsy and their parents identified CYP51A1 as a plausible candidate gene linked to the disease." (PMID 40659633, 2025). "Targeting CYP51A1 could therefore offer a promising sterol-based therapeutic approach for neurodegenerative and neurodevelopmental disorders." (PMID 40659633, 2025).
CYP51A1 also shares sentences with these, for which no sentence is quoted: Chagas disease (22 papers); infection (10); parasitemia (5); Candida infections (4); Hepatic steatosis (3); steatosis (3); tuberculosis (3); candidiasis (2); cystic fibrosis (2); dyslipidemia (2); Eumycetoma (2); Hepatomegaly (2); hypercholesterolaemia (2); lung diseases (2); malaria (2); mucormycosis (2); mycoses (2); trypanosomiasis (2); acne (1); cardiovascular diseases (1); cholestasis (1); Cirrhosis (1); co-infection (1); coccidioidomycosis (1); cognitive decline (1); cryptococcosis (1); cutaneous leishmaniasis (1); cyst (1); dementia (1); dermatophytosis (1).
A further 25 diseases each share a sentence with CYP51A1 in 1 paper.